SIRT2 (sirtuin 2)
Diseases named in the same sentence as SIRT2 in open-access papers (continued):
Sharing a sentence is not in itself a finding about the gene and the disease.
infection (continued). "SIRT2 is the only major Sirtuin that is primarily localized in the cytoplasm; however, during mitosis and pathogen infection, SIRT2 shuttles the nucleus and regulates chromatin condensation." (PMID 40317067, 2025). "SIRT2 is the most widely studied sirtuin in the context of infection and multiple SIRT2-targeted modulators have been reported to antagonize the replication of one or more intracellular pathogens." (PMID 39458938, 2024). "The AKT (aka protein kinase B, PKB; a serine/threonine kinase) pathway has been studied in the context of SIRT2 modulation during infection." (PMID 39458938, 2024). "SIRT2 is relocalized from the cytoplasm to the nucleus following infection with the pathogen, where it supports replication of the bacteria, at least in part, by reprograming host cell transcription to prevent premature death of the infected cell." (PMID 39458938, 2024). "SIRT2 impacts numerous cellular functions, ranging from innate defenses to transcription to metabolism, providing many opportunities for SIRT2 modulators to influence the course of an infection." (PMID 39458938, 2024). "Eldridge and Hamon found that 72% of the genes that gained SIRT2 and become repressed upon infection have TDP-43 at their TSS and showed that TDP-43 interaction with SIRT2 is essential for its enrichment at the TSS and H3K18 deacetylation during infection." (PMID 37762112, 2023). "To determine when SIRT2 acts during infection, we analyzed the ability of HCMV to proceed through each stage of the viral replication cycle following treatment with AGK2." (PMID 37916830, 2023). "Confocal microscopy analysis showed that the endogenous SIRT2 localizes to both the cytoplasm and the nucleus in uninfected cells and throughout infection." (PMID 37916830, 2023). "The results that we obtained after in vitro infection of glial cells directly support this model and suggest that SIRT2 plays an important role in brain injury and the HIV viral cycle, including maintaining the HIV reservoir in the brain." (PMID 36719240, 2023). "The results showed that knockdown of Scarb2, Pik3c3, and Sirt2 resulted in a significant decrease of the parasite load in comparison to control cells after 48 h of infection." (PMID 37915600, 2023). "We find that SIRT2 interacts with and modulates the acetylation level of cell cycle proteins during infection, including the cyclin-dependent kinase 2 (CDK2)." (PMID 37916830, 2023). "Focusing on these early infection time points, we next define temporal SIRT2 protein interactions and deacetylation substrates by using mass spectrometry-based interactome and acetylome analyses." (PMID 37916830, 2023). "Altogether, our analysis of temporal protein interactions suggests that SIRT2 is poised to broadly regulate cellular processes related to gene expression and cell cycle progression during infection." (PMID 37916830, 2023). "RUVBL2, ADNP, SF3A2, CDK2, PRKDC, and NONO were particularly interesting as the increase in acetylation following SIRT2 inhibition temporally aligned with the time point of maximal interaction with SIRT2 during infection." (PMID 37916830, 2023). "Infecting mouse bone-marrow-derived macrophage (BMDM) cells or mice with wildtype S. flexneri increased SIRT2 protein and mRNA levels while infection with the IpaJ deletion strain or IpaJ/VirA double deletion strain did not significantly change SIRT2 levels." (PMID 35918380, 2022). "Given the role Sirtuins have in maintaining genome integrity upon stress, we examined the consequences of SIRT2 inhibition on DNA damage accumulation during infection." (PMID 34929015, 2021). "In this study we show that SIRT2 activity protects host cells from DNA damage and promotes host cell survival during infection with L. monocytogenes." (PMID 34929015, 2021). "In agreement with CFU enumeration, quantification of Lm-GFP signal shows that during the early phases of infection both wildtype and Sirt2-/- cells support bacterial growth up to ~13 hours post infection." (PMID 34929015, 2021).
infection (continued). "Upon infection SIRT2 becomes enriched on chromatin at the transcriptional start sites (TSSs) of certain genes and induces deacetylation of H3K18 independently of the cell cycle." (PMID 34929015, 2021). "In fact, SIRT2 and TDP-43 function with genomic DNA:RNA hybrids called R-loops to reduce the accumulation of host DNA damage caused by infection." (PMID 34929015, 2021). "Taken together these data show that infection enhances the interaction between SIRT2 and TDP-43 in the nucleus, and that TDP-43 is necessary for the infection-induced enrichment of SIRT2 at the chromatin level to specific genetic locations." (PMID 34929015, 2021). "Such SIRT2 activity has a crucial role in promoting host cell viability during infection, allowing for better survival upon heavy intracellular bacterial burden, and resulting in enhanced infection by L. monocytogenes." (PMID 34929015, 2021). "We previously identified Ser25 as a residue on SIRT2 that was dephosphorylated upon infection and was necessary for SIRT2 to become enriched at chromatin." (PMID 34929015, 2021). "Consistent with our CFU data, cells expressing WT H3 show significantly reduced levels of InlC 24 hours post infection when treated with AGK2 indicating a stunted infection when SIRT2 is inhibited." (PMID 34929015, 2021). "On the contrary, in cells overexpressing RNaseH1, which lack R-loops, the infection-induced interaction between SIRT2 and TDP-43 is inhibited suggesting that R-loops are required for SIRT2:TDP-43 complex formation in response to infection." (PMID 34929015, 2021). "One such example is the hijacking of a host deacetylase called SIRT2 which upon infection localises to chromatin, specifically modifies lysine 18 of histone H3 and promotes intracellular bacterial growth." (PMID 34929015, 2021). "The results presented here define H3K18 deacetylation by SIRT2 as the key factor required for protection from DNA damage during infection." (PMID 34929015, 2021). "Our previous work showed that SIRT2 was recruited to the TSSs of a subset of genes which are repressed during infection." (PMID 34929015, 2021). "This work highlights novel functions of TDP-43 and R-loops during bacterial infection and identifies the mechanism through which L. monocytogenes co-opts SIRT2 to allow efficient infection." (PMID 34929015, 2021). "Recent studies have demonstrated that SIRT1 and SIRT2 are promising antiviral targets because of their specific connection to numerous metabolic and regulatory processes affected during infection." (PMID 33669990, 2021). "Consistent with its potential role in DDR during infection, our previously published SIRT2 interactome identified many DNA damage sensor and repair proteins including KU70/KU80, RPA1, FEN1 and PARP1." (PMID 34929015, 2021). "This increase is similar to that observed following infection, suggesting that S25 dephosphorylation has a role in regulating this interface between SIRT2 and TDP-43." (PMID 34929015, 2021). "In our previous work we demonstrated that SIRT2 targeted genes are also transcriptionally repressed during infection in a SIRT2 activity-dependent manner." (PMID 34929015, 2021). "Spleens from wildtype and Sirt2-/- mice were collected 72 hours after intravenous infection with L. monocytogenes and levels of γH2Ax were assessed by immunoblotting." (PMID 34929015, 2021). "We show that SIRT2-mediated H3K18 deacetylation counteracts infection-induced DNA damage and identify the molecular complex at play." (PMID 34929015, 2021). "Further in silico analysis of previously identified infection-dependent SIRT2-repressed genes showed that 72% of these have TDP-43 present at their TSSs by ChIP-seq (ENCODE portal)." (PMID 34929015, 2021). "Consistent with the alamarBlue assay microscopic analysis shows that by 24 hours post infection fewer Sirt2-/- cells survive infection." (PMID 34929015, 2021).
infection (continued). "During infection, nuclear import of SIRT2, mediated in part by importin IPO7; and dephosphorylation of SIRT2 at serine 25 to permit chromatin binding, enable H3K18 deacetylation." (PMID 34929015, 2021). "Altogether, our data demonstrate that TDP-43 is required for the execution of SIRT2-dependent H3K18 deacetylation during infection, and for the advantage SIRT2 can confer to L. monocytogenes during infection." (PMID 34929015, 2021). "Since SIRT2 modulates the acetylation levels of histone H3K18 upon infection with Listeria monocytogenes, we analyzed H3K18 acetylation upon Mtb infection and AGK2 treatment in mouse peritoneal macrophages." (PMID 32697192, 2020). "To corroborate our ex vivo results which emphasized the importance of SIRT2 inhibition in T cells for restricting intracellular Mtb growth, we performed infection experiments in Rag1-/- mice that lack mature B and T cells." (PMID 32697192, 2020). "Deacetylation of H3K18 appears to play an important role during infection, as inhibition or knockdown of either SIRT2 or PPM1A/PPM1B suppresses bacterial intracellular survival without affecting bacterial invasion." (PMID 32380645, 2020). "SIRT2 mutants did not display significantly reduced infection; however, sirtinol treatment led to a strong reduction in infection of SIRT2 mutant flies." (PMID 31289184, 2019). "Higher expression of SIRT2 leads to activation of AKT/GSK3β/β catenin signalling pathway during the infection." (PMID 30452468, 2018). "To understand the kinetics of SIRT2 expression during the course of infection, we have measured the mRNA and protein levels at different time intervals." (PMID 30452468, 2018). "In the transcript level, SIRT2 shows a 15-fold upregulation at 6 h post infection compared to control." (PMID 30452468, 2018). "At 10 days post infection, SIRT2-/- mice show reduction in body weight and increase in the bacterial burden in Peyer’s patch but do not show any change in serum cytokine level." (PMID 30452468, 2018). "For example, Listeria monocytogenes induces deacetylation of H3K18 mediated by the host deacetylase SIRT2 to promote infection in mammal cells." (PMID 30143616, 2018). "To understand the expression profile of SIRT2 during the course of infection, we have infected DCs with Salmonella and monitored its mRNA expression." (PMID 30452468, 2018). "The upregulation of SIRT2 expression in due course of infection suggests its involvement in bacterial pathogenesis." (PMID 30452468, 2018). "As per our knowledge, this is the first instance where SIRT2 expression has been measured in DCs during infection." (PMID 30452468, 2018). "From a translational perspective, it was important to define the impact of SIRT2 in preclinical models of infection." (PMID 28894448, 2017). "Listeria monocytogenes promoted SIRT2-dependent histone H3 deacetylation and redirected host gene expression to favor infection." (PMID 28894448, 2017). "Nonetheless, these results support the clinical development of SIRT2 inhibitors regarding their infection-related safety profile." (PMID 28894448, 2017). "Previous studies have demonstrated a role of Sirt2 both in inflammation and in infection by the intracellular pathogen L. monocytogens." (PMID 26135889, 2015). "Infection with the intracellular pathogen Listeria monocytogenes induces translocation of Sirt2 from the cytosol to the nucleus where it deacetylates histone H3 on lysine 18, thus inducing subsequent gene repression." (PMID 26135889, 2015). "In fact, we confirmed that ablation of Sirt2 in BMDM led to increased levels of IL-6 upon infection with M. tuberculosis." (PMID 26135889, 2015). "In this study, we expanded the research on the role of Sirt2 in infection, by investigating the impact of myeloid Sirt2 expression in M. tuberculosis infection." (PMID 26135889, 2015).
infection (continued). "As for bacterial infection, myeloid Sirt1 expression was shown to have little influence in Gram-negative toxin-induced shock or Gram-positive bacteremia, whereas ablation of Sirt2 profoundly changed the outcome of infection with L. monocytogenes." (PMID 26135889, 2015). "All 3 shRNAs against either SIRT1 or SIRT2 significantly reduced their target RNA levels and protein accumulation in the infected cells 48 hours after the last infection of these viruses." (PMID 23460888, 2013). "However, during mitosis and pathogen infection, SIRT2 shuttles to the nucleus and regulates chromatin condensation." (PMID 40317067, 2025). "We found that SIRT2 protein expression in BTCs was upregulated by B. abortus A19 infection at 48 h." (PMID 40317067, 2025). "Notably, G6PD, ACLY, and PGK1 were also detected in our IP-MS analysis of SIRT2 interactions during infection." (PMID 37916830, 2023). "Therefore, we next tested the kinetics of HCMV replication following SIRT2 inhibition by quantifying viral protein abundances throughout infection." (PMID 37916830, 2023). "Therefore, to investigate which of these cellular processes SIRT2 regulates during infection, we analyzed the temporal protein interactions of endogenous SIRT2." (PMID 37916830, 2023). "In vitro infection experiments using specific SIRT2 inhibitors suggest that specific targeting of SIRT2 could offer new therapeutic treatment options for HIV infections and their associated neurological dysfunction." (PMID 36719240, 2023). "Interestingly, at 48 h post-infection, a significant decrease of parasite load of 44%, 32%, and 26% was observed after knockdown of Scarb2, Pik3c3, and Sirt2, respectively." (PMID 37915600, 2023). "Therefore, given its diverse localization throughout infection, SIRT2 is poised to regulate different stages of the HCMV replication cycle." (PMID 37916830, 2023). "At earlier timepoints, where no infection-induced γH2Ax is observed, loss of either SIRT2 or TDP-43 does not result in heightened γH2Ax in cells." (PMID 34929015, 2021). "These additional features across the genome therefore could also be potential targets of SIRT2, which might contribute to the global effects observed during infection." (PMID 34929015, 2021). "Although infectious models are beyond the scope of this study, the effect of SIRT2 overexpression on NK cell function in infection is an interesting question that could be explored in future studies." (PMID 34155309, 2021). "Interestingly, infected Sirt2-/- cells begin to show signs of cell death starting from ~12 hours post-infection which intensifies further up to 24 hours." (PMID 34929015, 2021). "By contrast, the SIRT2 activity-independent gene ARAP2 shows a decrease in SIRT2 enrichment during infection which is not altered by the loss of TDP-43." (PMID 34929015, 2021). "Moreover, Resveratrol administration attenuates infection in acute and chronic Mycobacterium tuberculosis infection, while SIRT-2 is dispensable in the infection." (PMID 34485381, 2021). "Similarly to what is observed upon blocking SIRT2, TDP-43 silencing also causes a reduction in bacterial numbers 24-hours post infection, where 50% fewer bacteria were recovered relative to scramble controls." (PMID 34929015, 2021). "The impact of SIRT2 on infection-induced DNA damage was also determined in vivo." (PMID 34929015, 2021). "Similarly, Listeria monocytogenes directly hijacks PPM1A and PPM1B to dephosphorylate and translocate SIRT2 into the nucleus to promote effective infection." (PMID 33882943, 2021). "Therefore, DNA damage also accumulates in vivo within organs that are targeted during infection in a Sirt2-/- background." (PMID 34929015, 2021). "Given the roles of Sirtuins and H3K18 deacetylation in maintaining genome integrity, we hypothesised that SIRT2 could mitigate infection-induced genotoxic stress in order to better maintain the intracellular replicative niche." (PMID 34929015, 2021).
infection (continued). "As previously demonstrated, infection causes significant recruitment of SIRT2 to the TSSs of MYLIP, ERRC5, LEF1, SYDE2 and EHHADH but not ARAP2." (PMID 34929015, 2021). "Here, we show that Mtb upregulates one of the key epigenetic modulators, NAD+ dependent histone deacetylase Sirtuin 2 (SIRT2), which upon infection translocate to the nucleus and deacetylates histone H3K18, thus modulating the host transcriptome leading to enhanced macrophage activation." (PMID 32697192, 2020). "Pharmacological inhibition of SIRT2 restricts the intracellular growth of both drug-sensitive and resistant strains of Mtb and enhances the efficacy of front line anti-TB drug Isoniazid in the murine model of infection." (PMID 32697192, 2020). "We found that loss of SIRT1 or SIRT2 was not sufficient to block infection; however, sirtinol treatment of either mutant led to strong reductions in infection." (PMID 31289184, 2019). "However, post- infection AK7 treatment shows the rescue of T cell proliferation implicating the inhibitory role of SIRT2 in antigen presentation." (PMID 30452468, 2018). "This study shows the trade-off made by Salmonella where, in vitro infection mediated upregulation of SIRT2 enhances antimicrobial response, but simultaneous higher intracellular NO inhibits T cell response leading to impaired antigen presentation and successful pathogenesis." (PMID 30452468, 2018). "Two prior studies examined SIRT2 in the context of infection by intracellular bacteria." (PMID 28894448, 2017). "It is possible that either a more subtle immune alteration on the course of infection or a non-immune mechanism, such as metabolic variations commanded by the absence or Sirt2, underlie our observations." (PMID 26135889, 2015). "Therefore, the clarification of the role of Sirt2 and other Sirts in infection is relevant for future clinical applications." (PMID 26135889, 2015). "In Staphylococcus aureus infection, SIRT2 may exacerbate the severity of the infection." (PMID 40317067, 2025). "The protein expression of seven proteins (CD8A, ST1A1, AXIN1, FGF-5, MMP-10, HGF, SIRT2) was significantly decreased and the protein expression of two proteins (MMP-1, TNFRSF9) was significantly increased in caspase-1-deficient cells compared to Cas9 cells following HK1651 infection." (PMID 40137780, 2025). "A similar inhibitory effect on HBV RNA accumulation and promoter activity was observed for FLS-359; in this study, the SIRT2 modulator was also shown to inhibit the establishment of cccDNA at a point after the virus had entered the cell, when the drug was present at the start of the infection." (PMID 39458938, 2024). "However, a subsequent report showed that infection induces a complex between SIRT2 and the phosphatases PPM1A and PPM1B that localizes to chromatin and leads to the dephosphorylation of SIRT2 S25, which is required for its nuclear accumulation and H3K18 deacetylation activity." (PMID 39458938, 2024). "In addition, the role of SIRT2 in infections has recently begun to be explored." (PMID 36719240, 2023). "In addition, SIRT2 plasma levels were similarly elevated after 1 year in the later-cART group compared with those of individuals that initiated cART within less than 3 months from infection." (PMID 36719240, 2023). "Therefore, TDP-43 is required for SIRT2-dependent H3K18 deacetylation during infection." (PMID 34929015, 2021). "Importantly, SIRT2 activity at chromatin is essential for efficient L. monocytogenes infection in vitro and in vivo though how bacterial hijacking of SIRT2 promotes infection remains unknown." (PMID 34929015, 2021). "In this study, using SARS2-N501YMA30-infected mice, we demonstrate that SIRT2 and NAD+ boosting protect aged mice from severe disease and lethal infection." (PMID 40220296, 2025). "By performing a Euclidean distance analysis of the viral proteome at all analyzed infection time points, we observed a temporal delay in HCMV protein levels upon SIRT2 inhibition." (PMID 37916830, 2023).